APC (APC regulator of Wnt signaling pathway)
Diseases named in the same sentence as APC in open-access papers (continued):
Sharing a sentence is not in itself a finding about the gene and the disease.
ameloblastoma (3 papers, 2016 to 2021). The most common odontogenic tumor, arising from the epithelial component of the embryonic tooth and usually affecting the molar-ramus region of the mandible or maxilla. "The results of this study indicated that there were APC gene mutations in the occurrence process of ameloblastoma, which mainly manifested as point mutation." (PMID 27065015, 2016). "Aside from the SMO mutations, APC mutations have been detected in 3/6 ameloblastomas, and CTNNB1, PIK3CA, SMARCB1, PTEN, CDKN2A mutations have been reported in a few cases and tend to occur in a non-mutually exclusive manner with BRAF p.V600E mutation and with each other." (PMID 35048058, 2021). "APC gene locus mutations may be related to appearance of some malignant phenotypes in ameloblastoma, which may provide the basis for assessing grade malignancy of ameloblastoma and judging the prognosis in clinic." (PMID 27065015, 2016). "APC mutation plays a certain role in monitoring the tumor malignant degree as it may indicate the transition process of ameloblastoma malignant phenotype." (PMID 27065015, 2016). "Inactivating APC mutation and CTNNB1 activating mutation leads to strong and aberrant cellular β-catenin accumulation, and such phenomena have been observed in some odontogenic epithelial tumors, including ameloblastoma and odontogenic carcinoma." (PMID 35048058, 2021). "Therefore, it is considered that, in the occurrence process of ameloblastoma, changes of APC gene occur in DNA level (i.e., changes in genetics)." (PMID 27065015, 2016). "Therefore, it was considered that, in the occurrence process of ameloblastoma, changes of APC gene took place in DNA level (i.e., changes in genetics)." (PMID 27065015, 2016). "Therefore, studying the function of the suppressor gene APC will have an important significance in learning the molecular mechanism of the occurrence and development of ameloblastoma." (PMID 27065015, 2016). "Therefore, the influence of APC gene changes on the occurrence of ameloblastoma is considered from genetics mechanism and epigenetic mechanism." (PMID 27065015, 2016). "Therefore, this study aimed to investigate the function of cancer suppressor gene APC is of significance in learning the molecular mechanism of occurrence and development of ameloblastoma." (PMID 27065015, 2016). "If this change affected the structure and functions of APC protein, the stability of APC protein complex would be affected to change the degradation of complex to β-catenin and promote occurrence of certain malignant phenotype (invasiveness and metastasis) in ameloblastoma." (PMID 27065015, 2016). "This indicated that the changes of methylation level in APC promoter region have not been found among the collected specimens of clinical ameloblastoma tissues." (PMID 27065015, 2016). "However, our experiments results suggested that no gene methylation occurred in APC gene promoter region of ameloblastoma tissues." (PMID 27065015, 2016). "No gene methylation changes exist in APC gene promoter region of ameloblastoma tissues." (PMID 27065015, 2016).
atherosclerosis (3 papers, 2015 to 2025). A disease characterized by the build-up of fatty material and calcium deposition in the arterial wall resulting in partial or complete occlusion of the arterial lumen. "Although it remains to be verified clinically whether combined APC treatment exhibits a “potent anti-atherogenic function”, it seems that APC more strongly attenuates the progression of atherosclerosis than statin alone in cholesterol-fed rabbits." (PMID 26220196, 2015). "However, in this study, there was no more research into the role of APC-DC in atherosclerosis." (PMID 36910156, 2023).
Cachexia (3 papers, 2016 to 2025). Severe weight loss, wasting of muscle, loss of appetite, and general debility related to a chronic disease. "In this model, a point mutation of the APC gene causes mice to develop multiple intestinal neoplasia beginning around 4 weeks of age, with cachexia onset by 14 weeks of age, and severe cachexia by 20–24 weeks of age." (PMID 40985218, 2025). "Moreover, relatively few murine models are used to generate cachexia (the vast majority being LLC in C57BL/6, and Colon-26 in Balb/c, tumor cells injection), while the use of transgenic mice is generally restricted to C57BL/6 APC+/min." (PMID 26900952, 2016).
CMMR-D syndrome (3 papers, 2020 to 2024). "When evaluating patients with early onset of multiple adenomatous polyps in the absence of proven APC germline mutations, the differential diagnosis needs to include attenuated-FAP, mutY homologue (MUTYH)-associated polyposis and constitutional mismatch repair deficiency (CMMRD) syndrome." (PMID 36002671, 2022).
COVID-19 (3 papers, 2021 to 2022). A disease caused by infection with severe acute respiratory syndrome coronavirus 2. "In addition, anaphase-promoting complex/cyclosome (APC/C), a cell cycle regulator complex, and chromosome segregation were enhanced in leukocytes during severe COVID-19." (PMID 35887528, 2022).
Crohn disease (3 papers, 2018 to 2023). A gastrointestinal disorder characterized by chronic inflammation involving all layers of the intestinal wall, noncaseating granulomas affecting the intestinal wall and regional lymph nodes, and transmural fibrosis. "It should be added that Yaeger et al51 found higher rates of KRAS (33%) and APC (39%) mutations in intestinal, mainly colorectal, carcinomas associated with Crohn disease in comparison with SB-PCCs related to Crohn disease of our study (0% and 8%, respectively)." (PMID 36812376, 2023).
duodenal adenocarcinoma (3 papers, 2021 to 2025). A carcinoma that arises from glandular epithelial cells of the duodenum. "However, in contrast to our data, approximately 30% of duodenal adenocarcinomas and most duodenal adenomas have APC mutations." (PMID 40463821, 2025). "However, the previous report only targeted sporadic lesions and found that less than 10% of duodenal adenocarcinomas had APC mutations." (PMID 40463821, 2025).
endometrioid carcinoma (3 papers, 2020 to 2024).
gastritis (3 papers, 2011 to 2021). Inflammation of the stomach. "In addition, APC is hypermethylated in gastritis associated with H. pylori infection, and bacterial elimination reduced the proportion of cases with hypermethylated APC promoters." (PMID 30781778, 2019).
germinoma (3 papers, 2011 to 2020). A malignant germ cell tumor arising in the central nervous system. "While this particular sample showed higher expression of GATA6, FOXA2, or HNF4A and hypermethylation of RASSF1, RUNX3, HIC1, or APC, its methylation pattern was partially common to that of germinomas or ECs." (PMID 32999426, 2020). "However, rather surprisingly, of the ‘top 14’ most frequently reported genes that are hypermethylated in human cancers, all of which were included in our array analysis, only RASSF1A, APC and ESR1 were methylated in the majority of YSTs and almost none were methylated in germinomas." (PMID 21712824, 2011).
head and neck cancer (3 papers, 2013 to 2022). A primary or metastatic malignant neoplasm affecting the head and neck. "This hypomethylated set of genes included many genes that have previously been shown to be methylated in head and neck cancer, including RASSF1, CHFR, RUNX3, APC, and CDKN2A (p16)." (PMID 23358896, 2013).
head and neck squamous cell carcinoma (3 papers, 2022 to 2024). A squamous cell carcinoma that arises from any of the following anatomic sites: lip and oral cavity, nasal cavity, paranasal sinuses, pharynx, larynx, and salivary glands. "In head and neck squamous cell carcinoma (HNSCC), the function of the APC tumor suppressor protein, essential for maintaining the integrity of the β-catenin destruction complex, is frequently disrupted." (PMID 39684225, 2024).
Hypercholesterolemia (3 papers, 2015 to 2022). An increased concentration of cholesterol in the blood. "Four disease–associated genes in the proband presented VUS: APC, APOB, DSG2, and DSP, respectively associated with familial adenoma polyposis, homozygous familial hypercholesterolemia and hereditary cardiac disease." (PMID 30233642, 2018).
Iron deficiency anemia (3 papers, 2016 to 2025). "A 13-year-old girl with genetically confirmed FAP (APC mutation c.3927_3931delAAAGA) presented with chronic lower gastrointestinal bleeding and iron deficiency anemia." (PMID 40706335, 2025). "Taken together, our results provide a new rationale and exciting therapeutic value of utilizing n–3 PUFAs to target CRC and associated anemia, particularly in cases involving APC mutation." (PMID 27769066, 2016).
ischemic stroke (3 papers, 2015 to 2022). A stroke disorder caused by obstruction of blood flow to the brain, due to thrombotic (local blood clot formation) or embolic (due to a blood clot or other material traveling from another site) event. "Compared to PBS and M0-EVs group, M2-EVs increased the number of NG2+Ki67+ and APC+Ki67+ cells after 28 days of tMCAO (p < 0.05), indicating M2-EVs could enhance oligodendrogenesis after ischemic stroke." (PMID 35547763, 2022).
kidney cancer (3 papers, 2015 to 2025). Primary or metastatic malignant neoplasm involving the kidney. "To date, we have found no literature on the association of APC mutations with kidney cancer or of BRCA1, BRCA2 or APC mutations with liposarcoma of any kind." (PMID 39702187, 2024). "For kidney cancer, a maximum sensitivity and specificity of 88% and 100%, respectively, were found for VHL, p16/CDKN2a, p14ARF, APC, RASSF1A, and Timp-3." (PMID 40141826, 2025).
malaria (3 papers, 2022 to 2024). Malaria is a serious and sometimes fatal disease caused by a parasite that commonly infects a certain type of mosquito which feeds on humans. "Although malaria parasites encode only a largely reduced set of recognizable APC/C components, all of which seem to be essential for parasite proliferation, it is tempting to speculate that PfARK1 degradation may similarly be mediated by APC-/C-dependent ubiquitination." (PMID 39235260, 2024). "During malaria, EPCR has been found to bind the P. falciparum erythrocyte-membrane-protein-1 (PfEMP1) to the same region as APC; therefore, it decreases the anticoagulant activity of APC and promotes thrombosis and obstruction of blood circulation." (PMID 35204613, 2022).
mesothelioma (3 papers, 2022 to 2025). A usually malignant and aggressive neoplasm of the mesothelium which is often associated with exposure to asbestos. "A meta‐analysis has further revealed that the APC gene is significantly hypomethylated in mesothelioma, while CDH1, ESR1, miR‐34b/c, PGR, RARβ, SFRP1, and WIF1 are significantly hypermethylated." (PMID 40904706, 2025). "A recent systematic review and quantitative meta-analysis of DNA methylation in mesothelioma found both significantly hypomethylated genes (APC) and hypermethylated genes (CDH1, ESR1, miR34b/c, PGR, RATO, SFRP1, and WIF1)." (PMID 38297314, 2024).
neuroendocrine tumors (3 papers, 2020 to 2026). "Compared with sporadic neuroendocrine tumors, which typically lack APC mutations, adenomas containing well-differentiated neuroendocrine tumor exhibited significantly higher nuclear β-catenin expression in their study." (PMID 40491286, 2026). "Estrella et al26 proposed that alterations in the APC/β-catenin pathway, central to FAP, may facilitate the development of well-differentiated neuroendocrine tumor components within intestinal adenomas." (PMID 40491286, 2026).
periodontitis (3 papers, 2021 to 2026). An acute or chronic inflammatory process that affects the tissues that surround and support the teeth. "The study indicated that HAMSCs promoted the osteogenic differentiation of LPS-induced HBMSCs via the ANRIL/miR-125a/APC axis, and offered a novel approach for periodontitis therapy." (PMID 33413674, 2021). "We also evaluated the mRNA expression levels of several Wnt ligands and other proteins involved in β-catenin stabilization and activation, such as E-cadherin, AXIN, APC and GSK3B using a GEO database for periodontitis (GSE223924) and oral carcinogenesis (GSE85195)." (PMID 40421179, 2025). "However, whether altered localization of E-cadherin, APC, GSK3B and/or AXIN proteins occur during periodontitis to drive oral carcinogenesis remains unknown." (PMID 40421179, 2025). "Additionally, transcriptional expression analysis of components of the β-catenin destruction complex during periodontitis revealed no changes in APC and GSK3B expression." (PMID 40421179, 2025). "Since the change in mRNA levels of APC, GSK3B and AXIN during periodontitis are not related to those observed during oral carcinogenesis, it seems unlikely that transcriptional regulation of components of β-catenin destruction complex would be playing a role in periodontitis and oral carcinogenesis." (PMID 40421179, 2025).
prostate adenocarcinoma (3 papers, 2013 to 2025). "Likewise, APC gene aberrations are commonly detected in prostate adenocarcinoma and have been reported to confer a significantly elevated risk of disease aggressiveness." (PMID 41463218, 2025).
Renal cyst (3 papers, 2012 to 2025). A fluid filled sac in the kidney. "Transgenic expression of a stabilized β-catenin or deficiency of APC in renal tubular epithelia leads to renal cystic disease, supporting the conclusion that ectopic canonical Wnt signaling is sufficient for cystogenesis." (PMID 22912798, 2012).
Salmonella Infections (3 papers, 2012 to 2021). Infections with bacteria of the genus SALMONELLA. "WT Salmonella also reduced the amount of APC/Axin-binding proteins, whereas levels of the APC/β-catenin complex were not significantly changed after Salmonella infection." (PMID 22509369, 2012). "Downregulation of the APC mRNA or APC haploinsufficiency did not influence Salmonella infection as assessed by the similar recovery of viable bacteria after infection, and the presence of Salmonella‐containing vacuoles within the infected cells, detected by LPS staining, 24‐hr postinfection." (PMID 31414579, 2019).
serous carcinoma (3 papers, 2016 to 2025). "APC promoter hypermethylation decreased the risk of the serous carcinoma histotype." (PMID 27670526, 2016). "Therefore, APC promoter hypermethylation may be a potential drug target for serous carcinoma." (PMID 27670526, 2016). "The pooled OR indicated that APC promoter hypermethylation was significantly lower in serous carcinoma than in non-serous carcinoma (OR = 0.56, P = 0.02)." (PMID 27670526, 2016).
small cell lung carcinoma (3 papers, 2010 to 2023). Small cell lung cancer (SCLC) is a highly aggressive malignant neoplasm, accounting for 10-15% of lung cancer cases, characterized byrapid growth, and early metastasis. "In small-cell lung cancer (SCLC), the mutation in APC and CHD8, which inhibits transcription mediated by CTNNB1, is related to the relapse of SCLC." (PMID 37190019, 2023).
thyroid (3 papers, 2017 to 2023). "In recent years, several studies identified genes that cooperate with RAS mutations in the pathogenesis or progression of thyroid and other types of cancers, such as NF1, APC, PTEN, KEAP1, NF2 and others." (PMID 34065786, 2021). "APC has been found to be expressed in normal as well as in neoplastic human thyroid tissue, in which multiple forms of specific RNA transcripts have been detected; it may be hypothesized that alterations in APC are likely candidates for a pathogenic role in thyroid tumorigenesis." (PMID 28410400, 2017).
urothelial carcinoma (3 papers, 2011 to 2016). A malignant neoplasm derived from the transitional epithelium of the urinary tract (urinary bladder, ureter, urethra, or renal pelvis). "Evidence of activation of Wnt signaling in urothelial carcinoma also comes from other studies that identified frequent gene silencing of endogenous Wnt inhibitors and less frequent APC mutations in bladder cancer." (PMID 22325146, 2012). "Mutations of APC have also been associated with worse outcome in urothelial carcinomas." (PMID 27077911, 2016). "Moreover, missense mutations in APC were linked to worse disease outcome in invasive urothelial carcinomas, suggesting functional relevance of point mutated APC protein in the development of extra-intestinal tumors." (PMID 21859464, 2011). "The authors concluded that alteration of APC and β-catenin are rare events in urothelial carcinomas." (PMID 22325146, 2012).
uterine cancer (3 papers, 2013 to 2023). Primary or metastatic malignant neoplasm involving the uterine corpus and/or the cervix. "2/11 positive associations involved stop-gain mutations in the APC gene, one in colorectum and one in uterine carcinoma." (PMID 29748584, 2018).
22q11.2 deletion syndrome (2 papers, 2021 to 2025). 22q11.2 deletion syndrome (DS) is a chromosomal anomaly which causes a congenital malformation disorder whose common features include cardiac defects, palatal anomalies, facial dysmorphism, developmental delay and immune deficiency. "Considering a diagnosis of 22q11.2 deletion syndrome, we performed CMA that not only confirmed our diagnosis, but also pointed out an additional de novo 5q21.3q22.2 microdeletion, encompassing APC gene." (PMID 33588901, 2021).